CCKAR (cholecystokinin A receptor)
Description:
Receptor for cholecystokinin. Mediates pancreatic growth and enzyme secretion, smooth muscle contraction of the gall bladder and stomach. Has a 1000-fold higher affinity for CCK rather than for gastrin. It modulates feeding and dopamine-induced behavior in the central and peripheral nervous system. This receptor mediates its action by association with G proteins that activate a phosphatidylinositol-calcium second messenger system.
Synonyms: CCK-AR; CCK1-R; CCKRA; CCK1R; CCK-1R; CCK-A
Tractability: Small molecule: an approved drug acts on it; a structure with a bound ligand is known; a high-quality ligand is known; it belongs to a druggable protein family. Antibody: its Gene Ontology location is reachable by antibodies, with high confidence; UniProt places it where antibodies can reach, with medium confidence; UniProt predicts a signal peptide or a membrane-spanning region. PROTAC: a small molecule that binds it is known. Other modalities: an approved drug acts on it.
Target class: Short peptide receptor (family A GPCR); Peptide receptor (family A GPCR); Cholecystokinin receptor; Family A G protein-coupled receptor; Membrane receptor
Chemical probes: CHEMBL1773877, CHEMBL1933104
Safety:
Unwanted effects reported when the protein is acted on. In parentheses: how it was acted on, where the effect was seen, and who reports it.
gallbladder contraction (Bowes et al. (2012): activation, gastrointestinal; Lynch et al. (2017): activation, acute dosing, nervous system, gallbladder, gastrointestinal)
abdominal pain hypersenstivity (activation, acute dosing; nervous system, gallbladder, gastrointestinal; source: Lynch et al. (2017))
activation of dopamine-mediated behaviour (activation; gastrointestinal; source: Bowes et al. (2012))
anxiety (activation, chronic dosing; nervous system, gallbladder, gastrointestinal; source: Lynch et al. (2017))
bloating (activation, acute dosing; nervous system, gallbladder, gastrointestinal; source: Lynch et al. (2017))
cholelethiasis (inhibition, acute dosing; nervous system, gallbladder, gastrointestinal; source: Lynch et al. (2017))
cholestasis (inhibition, acute dosing; nervous system, gallbladder, gastrointestinal; source: Lynch et al. (2017))
decreased body temperature (activation, acute dosing; nervous system, gallbladder, gastrointestinal; source: Lynch et al. (2017))
decreased eating (activation, acute dosing; nervous system, gallbladder, gastrointestinal; source: Lynch et al. (2017))
decreased food intake (activation; gastrointestinal; source: Bowes et al. (2012))
decreased gastric emptying (activation, acute dosing; nervous system, gallbladder, gastrointestinal; source: Lynch et al. (2017))
decreased gastrointestinal transit (activation, acute dosing; nervous system, gallbladder, gastrointestinal; source: Lynch et al. (2017))
decreased locomotor activity (activation, acute dosing; nervous system, gallbladder, gastrointestinal; source: Lynch et al. (2017))
decreased sleep (activation, chronic dosing; nervous system, gallbladder, gastrointestinal; source: Lynch et al. (2017))
fatigue (activation, chronic dosing; nervous system, gallbladder, gastrointestinal; source: Lynch et al. (2017))
gas (activation, acute dosing; nervous system, gallbladder, gastrointestinal; source: Lynch et al. (2017))
increased blood pressure (activation, chronic dosing; nervous system, gallbladder, gastrointestinal; source: Lynch et al. (2017))
increased development of gallstones (inhibition; gastrointestinal; source: Bowes et al. (2012))
increased eating (inhibition, acute dosing; nervous system, gallbladder, gastrointestinal; source: Lynch et al. (2017))
increased gastric emptying (inhibition, acute dosing; nervous system, gallbladder, gastrointestinal; source: Lynch et al. (2017))
increased gastrointestinal motility (activation; gastrointestinal; source: Bowes et al. (2012))
increased heart rate (activation, chronic dosing; nervous system, gallbladder, gastrointestinal; source: Lynch et al. (2017))
increased intestinal transit (inhibition, acute dosing; nervous system, gallbladder, gastrointestinal; source: Lynch et al. (2017))
nausea (activation, acute dosing; nervous system, gallbladder, gastrointestinal; source: Lynch et al. (2017))
pancreatic enzyme secretion (activation; gastrointestinal; source: Bowes et al. (2012))
Gene: Protein-coding gene on chromosome 4 (26,481,396 to 26,490,484, reverse strand). Ensembl gene ENSG00000163394.
Subcellular location: Cell membrane
Subcellular location (Human Protein Atlas): Cytosol; Plasma membrane; Nucleoplasm
Pathways (Reactome):
Signal Transduction: G alpha (q) signalling events; Peptide ligand-binding receptors
Gene Ontology:
Molecular function: cholecystokinin receptor activity; peptide hormone binding; protein binding; G protein-coupled receptor activity
Biological process: cholecystokinin signaling pathway; cellular response to hormone stimulus; G protein-coupled receptor signaling pathway; phospholipase C-activating G protein-coupled receptor signaling pathway; regulation of hormone secretion
Cellular component: membrane; plasma membrane
Genetic constraint (gnomAD): Loss-of-function variants: 22 observed, 31.05 expected, observed/expected ratio (o/e) 0.71, 90% interval 0.5 to 1.01. The upper end of that interval is the gene's LOEUF score, 1.01, which puts it in group 4 of 6, group 1 being the genes least tolerant of losing a copy. Missense variants: 544 observed, 568.72 expected, observed/expected ratio (o/e) 0.96, 90% interval 0.89 to 1.03. Synonymous variants: 233 observed, 226.28 expected, observed/expected ratio (o/e) 1.03, 90% interval 0.93 to 1.15.
Homologues: Orthologues: chimpanzee CCKAR (99% identical), macaque CCKAR (98% identical), guinea pig CCKAR (92% identical), rat Cckar (92% identical), mouse Cckar (91% identical), dog CCKAR (89% identical), pig CCKAR (89% identical), rabbit CCKAR (88% identical), tropical clawed frog cckar (70% identical), zebrafish CCKAR (58% identical), Drosophila melanogaster CCKLR-17D1 (36% identical), Drosophila melanogaster CCKLR-17D3 (34% identical). Paralogues in human: CCKBR (48% identical), NPFFR1 (27% identical), NPFFR2 (24% identical), QRFPR (23% identical), HCRTR2 (23% identical), HCRTR1 (23% identical), FFAR4 (21% identical), OXTR (21% identical), GALR1 (21% identical), AVPR1B (21% identical), AVPR1A (20% identical), AVPR2 (19% identical), and 4 more.
Diseases named in the same sentence as CCKAR in open-access papers:
CCKAR is named in the same sentence as 83 diseases in open-access papers, as found by Europe PMC text mining. Sharing a sentence is not in itself a finding about the gene and the disease. The quoted sentences say what the papers report.
Obesity (20 papers, 2007 to 2025). Accumulation of substantial excess body fat. "Here, the authors show that antagonizing cholecystokinin and its receptor, CCKAR, in the lung attenuates obesity-associated airway hyperresponsiveness in mice." (PMID 36599824, 2023). "Our results support a model in which elevated CCK level associated with obesity increases CCKAR signaling in the lung to constrict ASM cells to drive bronchoconstriction and AHR." (PMID 36599824, 2023). "Loss of CCKAR due to spontaneous mutations decreased satiety and increased food intake and obesity in humans and rats." (PMID 35741846, 2022). "CCKAR variants and mutations have been reported to be associated with obesity in humans." (PMID 38019584, 2024). "Here we report that cholecystokinin—a metabolic hormone best known for its role in signaling satiation and fat metabolism—is increased in the lungs of obese mice and that pharmacological blockade of cholecystokinin A receptor signaling reduces obesity-associated airway hyperresponsiveness." (PMID 36599824, 2023). "While our studies focused largely on inhibiting CCKAR-mediated contraction, the absence of effect of CCKAR antagonists on BAL cell differential counts or inflammatory cytokines nevertheless suggests that blocking CCKAR-mediated ASM contraction is sufficient to suppress obesity-associated AHR." (PMID 36599824, 2023). "Thus, while CCK receptors are also expressed in non-ASM cells in which they mediate cellular processes in the context of other lung disorders, CCKAR signaling in ASM cells appears to be the major driver of obesity-associated AHR." (PMID 36599824, 2023). "Indeed, blocking CCKAR using potent CCKAR antagonists attenuates obesity-associated AHR in two different obese mouse models." (PMID 36599824, 2023). "The region with CCKAR has previously been linked with obesity." (PMID 22028671, 2011). "We also found that CCK is elevated in the lungs of mouse models of obesity-associated asthma, which implied that CCK/CCKAR mediates AHR in the obese." (PMID 36599824, 2023). "Our data using obese mouse models further demonstrate that antagonizing CCK/CCKAR in the lung attenuates obesity-induced AHR." (PMID 36599824, 2023). "Our studies provide critical preclinical evidence that supports the development of CCKAR antagonists into new therapeutics to treat asthma patients with obesity." (PMID 36599824, 2023). "Together, our results reveal an unexpected role for cholecystokinin in the lung and support the repurposing of cholecystokinin A receptor antagonists as a potential therapy for asthma patients with obesity." (PMID 36599824, 2023). "Our study uncovers a previously undescribed mechanism for obesity-associated asthma that is based on the largely unexplored ability of CCK hormone and its receptor CCKAR in promoting ASM contraction." (PMID 36599824, 2023). "Our present study reveals that CCKAR mediates CCK-induced contraction of ASM cells and that CCK/CCKAR signaling is a mechanism underlying obesity-induced AHR in mice." (PMID 36599824, 2023). "CCK regulates appetite and food intake primarily through CCKAR on the vagal afferent neurons, making CCKAR an attractive therapeutic target for obesity." (PMID 34556862, 2021). "A total of 12 significant SNPs associated with BMI were identified, of which 7 SNPs were also significantly associated with obesity, including rs1337406 (WLS), rs673612 (NTNG1), rs4449107 (FAM84A), rs9820485 (STAG1), rs73247924 (CCKAR), rs2083069 (ACADSB), and rs4942190 (DNAJC15)." (PMID 38807991, 2024). "Furthermore, our study provides direct pre-clinical evidence for the repurposing of potent CCKAR antagonists as new, potentially effective therapies for asthma patients with obesity." (PMID 36599824, 2023). "Our data showing elevated CCK in the lungs of obese mice suggest that a heightened CCK/CCKAR signaling and subsequent ASM contraction may contribute to the development of obesity-associated AHR." (PMID 36599824, 2023).
Obesity (continued). "Our data suggest that, at least in the mouse with obesity-associated AHR, the heightened CCK/CCKAR signaling in the lung appears to lead to increased ASM contraction that is independent of airway inflammation as CCKAR antagonists did not alter markers of inflammation." (PMID 36599824, 2023). "Our experimental results also do not rule out the possibility that CCKAR signaling in the CNS affects obesity-associated AHR." (PMID 36599824, 2023). "CCKAR has been developed as a promising target to treat obesity in humans." (PMID 35741846, 2022). "Gallbladder hypomotility is also revealed in some subjects without gallstones under several conditions: pregnancy, total parenteral nutrition, celiac disease, oral contraceptives and conjugated estrogens, obesity, diabetes, the metabolic syndrome, and administration of CCKAR antagonists." (PMID 33260332, 2020). "Thus, our data showing that CCKAR antagonists attenuated AHR support the idea that these drugs could potentially be repurposed for the treatment of asthma patients with obesity." (PMID 36599824, 2023). "Tissue-specific conditional CCK or CCKAR knockout in obese mice may be needed to completely rule out the possible role of CCK/CCKAR in the brainstem in modulating obesity-associated AHR." (PMID 36599824, 2023). "Antagonizing such elevated CCK/CCKAR signaling in the ASM blocks obesity-induced AHR and thus presents a completely new way to treat asthma in patients with obesity." (PMID 36599824, 2023). "Since CCK has two known receptors, CCKAR and CCKBR20, we then tested if a specific receptor signaling pathway is more relevant in the islet or changed by obesity." (PMID 32071395, 2020). "In addition, clinical studies have found that CCK, CCKAR, and CCKBR are involved in many metabolic disorders such as cholesterol gallstone disease, obesity, diabetes, and the metabolic syndrome, as well as some gastrointestinal tract disorders, brain diseases, and cancers in the digestive system." (PMID 33260332, 2020).
gallstones (9 papers, 2007 to 2025). Solid crystalline precipitates in the biliary tract, usually formed in the gallbladder, resulting in the condition of cholelithiasis. "It was aimed to assess the association of four polymorphisms and relative haplotypes in the ATP binding cassettes and cholecystokinin A receptor (rs6720173, rs11887534, rs4148217, rs1800857) with the risk of gallstone." (PMID 29511480, 2017). "CCKAR is known to be involved in the main pathway for gallbladder contraction and association of gallstones with GBC is also known." (PMID 25025063, 2014). "Based on the finding that the CCKAR gene is Lith13 located on chromosome 5 in mice, it has been revealed that genetic variations in the human CCKAR gene are an important risk factor for gallstone formation." (PMID 33260332, 2020). "Furthermore, epidemiological investigations and clinical studies have found that the CCKAR gene is an important gallstone gene that is associated with increased prevalence of cholesterol gallstone disease in humans." (PMID 33260332, 2020). "Thus, it is still unclear whether variants in the CCKAR gene are associated with increased gallstone prevalence in humans and whether there are mutations in the CCKAR gene in gallstone patients." (PMID 33260332, 2020). "Moreover, abnormal processing of CCKAR is found to be associated with gallstones and obesity." (PMID 25025063, 2014). "The reduced levels of gallbladder CCKAR lead to decreased gallbladder motility, weakened gallbladder contractions, and promote the formation of gallstones." (PMID 39851308, 2025). "Other mutations and alterations have been described in different genes and proteins potentially involved in a higher risk of developing gallstones, such as ABCB11, cholesterol 7a-hydroxylase (CYPA1), APOB gene, and cholecystokinin A receptor (CCKAR)." (PMID 35207722, 2022). "More importantly, the CCKAR gene has been identified to be a critical gallstone gene, called Lith13, in inbred strains of mice by a powerful genetic technique, the quantitative trait locus (QTL) analysis." (PMID 33260332, 2020). "In addition, a comprehensive investigation is strongly needed to examine whether single nucleotide variants (SNVs) of the CCKAR gene play a role in increasing predisposition to the formation of biliary sludge and gallstones in pregnant women and in patients receiving TPN." (PMID 33260332, 2020). "The CCKAR gene has been identified to be an important gallstone gene, Lith13, in inbred mice by a powerful quantitative trait locus analysis." (PMID 33260332, 2020). "Therefore, the potent gallbladder-specific CCKAR-selective agonist is likely to offer a new strategy for preventing gallstone formation by increasing gallbladder emptying in women during pregnancy and in individuals with impaired gallbladder contractility." (PMID 33260332, 2020). "Based on the results from genetic analysis of Lith13 and pathophysiological studies of gallbladder and gallstone phenotypes in mice, it has been suggested that there is a possible relationship between the abnormality of the CCKAR gene and cholesterol gallstone formation in humans." (PMID 33260332, 2020). "Furthermore, genotyping and phenotyping studies have found that CCKAR is a key gallstone gene, Lith13, in mice." (PMID 33260332, 2020). "In addition to the same gallbladder phenotype, i.e., impaired gallbladder emptying in both CCK and CCKAR knockout mice, the identical evolutionary sequences from solid cholesterol crystals to gallstone formation are found in both strains of knockout mice." (PMID 33260332, 2020). "Notably, Lith13 is co-localized with a genetic biomarker D5Mit183 at roughly 30 centimorgans (cM), and within the Lith13 QTL region, the CCKAR gene is a powerful candidate for this gallstone gene." (PMID 33260332, 2020).
pancreatic cancer (8 papers, 2016 to 2026). "They demonstrated an effective treatment by using the promoter of CCKAR, suggesting the feasibility of pancreatic-cancer-specific promoter-based gene therapy in pancreatic cancer treatment." (PMID 29858085, 2018). "Furthermore, the versatile expression vector “VISA” (VP16-GAL4-WPRE integrated systemic amplifier) which contained the same tumor-specific CCKAR promoter was constructed to direct the expression of BikDD in pancreas cancer in vivo." (PMID 33381459, 2020). "Furthermore, down-regulated mRNAs of the kallikrein peptidase family (Klk1, Klk1b3, Klk1b5) and the cholecystokinin receptor type A (CCKAR), and expression of cdh2 coding for N-cadherin as well as somatostatin discriminated pancreatic tumors from pancreatic controls." (PMID 27769070, 2016).
Anxiety (5 papers, 2019 to 2025). Intense feelings of nervousness, tension, or panic often arise in response to interpersonal stresses. "Studies have shown that CCK gene variants may be associated with different anxiety phenotypes, and CCKAR may play a role in the development of panic comorbid with bipolar disorder." (PMID 40243462, 2025). "In conclusion, our study showed that CCKAR in mPOAGad2 neurons exert bidirectional control over anxiety-like and aggressive behaviors." (PMID 40933818, 2025). "In conclusion, these results imply that CCKAR acts as a molecular switch for CCS-induced concurrent anxiety-like and aggressive behaviors by modifying the excitability of mPOA GABAergic neurons." (PMID 40933818, 2025). "Collectively, the findings from both CCKAR loss- and gain-of-function experiments indicate that CCKAR activity in the mPOA is necessary and susceptible for the exhibition of CCS-induced co-occurring anxiety-like and aggressive behaviors." (PMID 40933818, 2025). "This suggests that a potential neural circuit conveying olfactory information to the mPOA may be involved in promoting anxiety-like and aggressive behaviors, subject to CCKAR regulation." (PMID 40933818, 2025). "Although studies have implicated CCKAR in spatial memory, food intake and olfactory recognition, whether CCKAR plays a role in anxiety and aggression remains unclear." (PMID 40933818, 2025). "Thus, GABAergic neurons and CCKAR in the mPOA may exert stressor-dependent effects on anxiety and aggression." (PMID 40933818, 2025). "Notably, MK-329, a selective antagonist of CCKAR, has been previously reported to impair olfactory recognition, while our findings demonstrate its ability to rescue CCS-induced anxiety." (PMID 40933818, 2025).
schizophrenia (4 papers, 2013 to 2021). A major psychotic disorder characterized by abnormalities in the perception or expression of reality. "This relation to dopamine release made CCKAR an interesting candidate gene for schizophrenia risk, since a theory about the origins of schizophrenia postulated that it is the result of excessive dopaminergic activity in the brain." (PMID 23341962, 2013). "In summary, the present study shows that variation in the CCKAR gene modulates language lateralization, with the schizophrenia risk allele C of the rs1800857 polymorphism being related to reduced functional asymmetry." (PMID 23341962, 2013). "The analysis of 16 schizophrenia-related polymorphisms revealed an association between the CCKAR gene and language lateralization assessed with the dichotic listening task." (PMID 23341962, 2013). "Abundant studies showed that DNA variations in the cholecystokinin A receptor (CCK-AR) gene contributed to the formation of schizophrenia and AHs." (PMID 34858129, 2021).